CRYBB1 (crystallin beta B1)
Description:
Crystallins are the dominant structural components of the vertebrate eye lens.
Synonyms: CATCN3; CTRCT17
Tractability: Small molecule: it has a high-quality binding pocket.
Gene: Protein-coding gene on chromosome 22 (26,599,277 to 26,619,630, reverse strand). Ensembl gene ENSG00000100122.
Gene Ontology:
Molecular function: protein binding; structural constituent of eye lens
Biological process: lens development in camera-type eye; visual perception
Genetic constraint (gnomAD): Loss-of-function variants: 16 observed, 30.82 expected, observed/expected ratio (o/e) 0.52, 90% interval 0.35 to 0.79. The upper end of that interval is the gene's LOEUF score, 0.79, which puts it in group 3 of 6, group 1 being the genes least tolerant of losing a copy. Missense variants: 299 observed, 367.9 expected, observed/expected ratio (o/e) 0.81, 90% interval 0.74 to 0.89. Synonymous variants: 127 observed, 144.37 expected, observed/expected ratio (o/e) 0.88, 90% interval 0.76 to 1.02.
Homologues: Orthologues: chimpanzee CRYBB1 (98% identical), macaque CRYBB1 (94% identical), dog CRYBB1 (82% identical), pig CRYBB1 (82% identical), rabbit CRYBB1 (81% identical), rat Crybb1 (81% identical), guinea pig CRYBB1 (80% identical), mouse Crybb1 (80% identical), zebrafish crybb1 (58% identical), tropical clawed frog crybb1 (58% identical). Paralogues in human: CRYBB3 (43% identical), CRYBB2 (42% identical), CRYBA1 (38% identical), CRYBA2 (38% identical), CRYBA4 (33% identical), CRYBG2 (31% identical), CRYBG1 (30% identical), CRYBG3 (27% identical), CRYGS (26% identical), CRYGC (25% identical), CRYGD (24% identical), CRYGA (24% identical), and 2 more.
Diseases named in the same sentence as CRYBB1 in open-access papers:
CRYBB1 is named in the same sentence as 21 diseases in open-access papers, as found by Europe PMC text mining. Sharing a sentence is not in itself a finding about the gene and the disease. The quoted sentences say what the papers report.
cataract (11 papers, 2008 to 2025). Partial or complete opacity of the crystalline lens of one or both eyes that decreases visual acuity and eventually results in blindness. "Vice versa, the expression of the CRYBB1-encoding gene is lower in vervet monkeys developing congenital cataracts." (PMID 40649110, 2025). "The primary expressed gene in the pseudo-albino brain tissue was CRYBB1, a Crystallin protein gene linked to the formation of eye lenses, optical transparency, cataracts, central circadian rhythm, fertility in mice, and cancer." (PMID 39063015, 2024). "Although congenital cataracts due to CRYBB1 gene mutations have been reported, mutations in this nucleotide were not previously detected." (PMID 32854469, 2020). "In conclusion, we report a novel mutation in the CRYBB1 gene causing anterior and posterior subcapsular cataracts, suggesting that the mutant gene affected the fetal nucleus in the late stages of development." (PMID 32854469, 2020). "Although a locus for late onset pulverulent cataracts was mapped previously to 9q13-q22, our findings implicate CRYBB1 as the first gene to be associated with autosomal recessive nuclear pulverulent cataracts." (PMID 19461930, 2009). "CRYBB1 mutations have been associated with a number of cataract subtypes (e.g. pulverulent and nuclear) and with additional developmental ocular abnormalities (microcornea)." (PMID 19461930, 2009). "In order to further delineate the molecular pathology of autosomal recessive cataracts, we investigated a consanguineous family with nuclear pulverulent cataracts and identified a novel germline CRYBB1 mutation." (PMID 19461930, 2009). "In conclusion, we report a novel nonsense mutation (Q223X) in CRYBB1 in a family with autosomal dominant congenital nuclear cataract." (PMID 18432316, 2008). "In addition, although a number of genetic causes of autosomal dominant pulverulent cataracts have been identified (including CRYBB1) this is the first gene to have been implicated in autosomal recessive nuclear pulverulent cataract." (PMID 19461930, 2009). "In patient 14, a novel duplication c.588_602dup (p.Gln197_Tyr201dup) in CRYBB1 was found in a patient with bilateral cataracts." (PMID 41155148, 2025). "For the lens, which is largely made up of crystallins, we find many crystallin genes (Crybb3, Cryba1, Crybb1, Crygc, Crygs, etc.)in our accelerated set of genes contributing to various forms of cataracts." (PMID 29035697, 2017). "Of these, mutations in 9 crystallin genes have been associated with autosomal dominant cataracts (CRYAA, CRYAB, CRYBB1, CRYBB2, CRYBA1/A3, CRYBA4, CRYGC, CRYGD, and CRYGS) but only 3 with autosomal recessive cataracts (CRYAA, CRYBB1, and CRYBB3)." (PMID 19461930, 2009).
Anxiety (4 papers, 2016 to 2025). Intense feelings of nervousness, tension, or panic often arise in response to interpersonal stresses. "Crybb1, a gene implicated in synaptic pruning, anxiety behavior and stress, was upregulated in both microglia clusters." (PMID 35031523, 2022). "Recent studies associate Gomafu with stress and anxiety and suggest that Gomafu can affect anxiety behaviors in mice by affecting the expression of the schizophrenia-related gene β-crystallin (Crybb1) through binding to PRC116." (PMID 27251103, 2016). "It has been proposed that GOMAFU negatively regulates genes involved in sustaining anxiety, like the Crybb1 gene." (PMID 40507852, 2025). "Further experiments revealed that Gomafu represses beta crystallin (Crybb1) expression by interacting with the polycomb repressive complex 1 (PRC1) in the Crybb1 promoter region to reduce anxiety-like behaviors in mice." (PMID 36226104, 2022).
congenital cataracts (4 papers, 2017 to 2022). "A subset of the 7-days radiation only DEG (Cryaa, Cryba1, Cryba2, Cryba4, Crybb1, Crybb2, Crybb3, Crygs, Bsfp1) were enriched in nuclear and congenital cataracts, however, these genes were not dysregulated at 1 month or 4 months." (PMID 36207342, 2022).
autosomal dominant congenital cataract (3 papers, 2008 to 2011). "All reported mutations of CRYBB1 associated with autosomal dominant congenital cataract occur in exon 6, which encodes the Greek key IV and the COOH-terminal arm." (PMID 18432316, 2008).
microphthalmia (2 papers, 2018 to 2025). Congenital or developmental anomaly in which the eyeballs are abnormally small. "Mice/humans with variants in other cataract-associated genes, such as crystallins can also manifest with complex features including corneal anomalies, iris hypoplasia and microphthalmia [(CRYAA; CRYBB1; CRYBA4]." (PMID 40301690, 2025).
Nystagmus (2 papers, 2011 to 2018). Rhythmic, involuntary oscillations of one or both eyes related to abnormality in fixation, conjugate gaze, or vestibular mechanisms. "In ADCC, p.Ser129Arg described in this study is the first mutation of CRYBB1 identified not in exon 6, which is responsible for bilateral dense nuclear cataract with microcornea and nystagmus in all affected members." (PMID 21972112, 2011).
schizophrenia (2 papers, 2020 to 2022). A major psychotic disorder characterized by abnormalities in the perception or expression of reality. "In addition, we found hypo-methylation and downregulation of two crystalline genes, CRYBB1 and CRYBB2, which were previously found to be associated with schizophrenia and autism-like behavior." (PMID 36012404, 2022).
Coats disease (1 paper, 2016). Coats disease (CD) is an idiopathic disorder characterized by retinal telangiectasia with deposition of intraretinal or subretinal exudates, potentially leading to retinal detachment and unilateral blindness. "Of the identified DCPs, several crystalline-related proteins, including CRYBB1, CRYBB2, CRYGS and CRYGD, were down-regulated in the AH from patients with Coats' disease." (PMID 27416065, 2016).
diabetes (1 paper, 2017). "Overall, we conclude that the syndromic diabetes presentation of the index case results from the combination of a heterozygous ABCC8-p.R825Q mutation causing diabetes and a homozygous CRYBB1-p.G71S mutation causing cataract." (PMID 29112131, 2017). "Our detailed genetic and familial study revealed that this disease association was rather explained by independent mutations in two genes that were known to cause diabetes (ABCC8) and congenital cataract (CRYBB1), respectively dominant and recessive, both of which with incomplete penetrance." (PMID 29112131, 2017).
periodontitis (1 paper, 2023). An acute or chronic inflammatory process that affects the tissues that surround and support the teeth. "Another member of Module 3, also regulated by PAX6, is CRYBB1, a gene that is over-expressed in periodontitis." (PMID 37834287, 2023).
renal cell carcinoma (1 paper, 2023). "The results showed that FUCA1 was down-regulated and SLC40A1, VSIG4, CRYBB1 and LIPA were up-regulated in renal cell carcinoma and 786-O, and the difference was statistically significant." (PMID 37361571, 2023).
cancer (3 papers, 2021 to 2025). A tumor composed of atypical neoplastic, often pleomorphic cells that invade other tissues. "In a similar vein, the activation of small heat shock proteins (CRYAA, CRYAB, CRYBB1), which are known as protectors against oxidative stress and apoptosis in normal and cancer cells, can be considered as a hallmark of generalized stress resistance." (PMID 41287033, 2025).
tumor (3 papers, 2021 to 2024). "Phenotype association analysis suggested all of hub genes involved in tumor development, and it seems CRYBB1, CEACAM4, and HAMP correlated with ccRCC progression more than another two (RIMBP3C and LYL1)." (PMID 34402193, 2021). "Spearman correlations analysis showed that CRYBB1, CEACAM4, HAMP, and LYL1 were highly positively associated with tumor‐infiltrating lymphocytes in ccRCC." (PMID 34402193, 2021). "The implication in sunitinib resistance, tumor‐infiltrating, and the progression and development in ccRCC was first uncovered for CRYBB1 and the prognostic implication in ccRCC was also first demonstrated for RIMBP3C in this study." (PMID 34402193, 2021). "The Hom-MG-1 subgroup highly expressed the innate characteristic genes of microglia (Tmem119, P2ry12, Crybb1, Cst1, Gpr34, and Cx3cr1), poorly expressed tumor activation-related genes, and expressed early activation genes to a certain extent (Jun, Junb, Jund, and Fos)." (PMID 39867913, 2024). "Tumor microenvironment analysis in TISIDB and GSE73731 confirmed that CRYBB1, CEACAM4, HAMP, and LYL1 were highly related to tumor‐infiltrating lymphocytes." (PMID 34402193, 2021). "Spearman correlations analysis indicated that CRYBB1, CEACAM4, HAMP, and LYL1 were positively related to different kinds of tumor‐infiltrating lymphocytes across many tumor types while RIMBP3C showed consistently statistical insignificance." (PMID 34402193, 2021).
CRYBB1 also shares sentences with these, for which no sentence is quoted: Microcornea (2 papers); nuclear cataract (2); age-related macular degeneration (1); Anterior polar cataract (1); autism (1); autosomal dominant cataracts (1); cataract - microcornea syndrome (1); neurological disorders (1).